HOXD10 (homeobox D10)
Diseases named in the same sentence as HOXD10 in open-access papers (continued):
Sharing a sentence is not in itself a finding about the gene and the disease.
tumor (continued). "HOXD10 acts as a tumor suppressor and suppresses invasion and migration of CCRCC cells by regulating E-cadherin and EMT processes." (PMID 34825321, 2022). "IHC staining showed that expression of HOXD10 and miR-501 was also negatively correlated in the subcutaneous tumor of nude mice." (PMID 34022794, 2021). "An elevated expression of HOXD10 led to tumor quiescence; it also has been reported as a TSG in pancreatic and cholangiocarcinoma." (PMID 33958005, 2021). "Functionally, HOXD10 acts as a tumor suppressor gene, in which HOXD10-expressing cells showed suppressed cell proliferation, colony formation ability, and migration and invasion capacity." (PMID 34790580, 2021). "The overexpression of HOXD10 can sufficiently upregulate the promoter activity and transcription level of miR-7, suggesting that HOXD10 exerts its tumor-suppressive function, at least in part, through miR-7." (PMID 34790580, 2021). "For example, HOXD10 (HGNC:5133) was a major factor that negatively regulates tumor metastasis, and the expression of the HODX10 gene in the CRC tissue with lymphatic metastasis was lower than that in tissues without lymphatic metastasis." (PMID 35087827, 2021). "Most of the miR-224-associated studies have been conducted in human cancer cells, with miR-224 reported to promote the expression of tumor invasion-associated proteins p-PAK4 and MMP-9 by directly targeting HOXD10." (PMID 34379706, 2021). "High expression of HOXD10 promotes tumor proliferation and migration, while low expression of HOXD10 can promote tumor invasion and metastasis by regulating AMOT-p80." (PMID 33763449, 2020). "The top 40 differential methylation genes were analyzed by differential methylation analysis, showing the higher HOXD10 methylation in carcinoma tissues vs. non-tumor tissues." (PMID 30683109, 2019). "When MSP was applied to tumour samples, a significant reduction of HOXD10, FGFR2 (P < 0.05), ITIH5 and RASAL3 (P < 0.001) promoter methylation was observed in DEC-treated mice." (PMID 30533020, 2018). "The tumor volume was smaller in HOXD10 re-expressed SMMC7721 cell xenograft mice compared to HOXD10 unexpressed SMMC7721 cell xenograft mice (P < 0.001)." (PMID 29075359, 2017). "The tumor weights were 0.17 ± 0.09 g vs. 0.06 ± 0.02 g (P < 0.05) in HOXD10 unexpressed and re-expressed SMMC7721 cell xenografts." (PMID 29075359, 2017). "The tumor volume in HOXD10 unexpressed and re-expressed SMMC7721 cell transplanted xenograft mice was 527.22 ± 271.23 mm3 vs. 212.00 ± 75.93 mm3." (PMID 29075359, 2017). "After serial sectioning, we observed that A673 sh.HOXD10 and sh.control tumor nodules in lungs were bigger with a higher amount of necrosis than the tumor nodules after injection of A673 cells with stable HOXD11 and HOXD13 knock down." (PMID 27363011, 2016). "To further elucidate the possible contribution of posterior HOXD genes to phenotype and tumor pathology of ES we analyzed contact dependent growth of HOXD10, HOXD11 and HOXD13 shRNA infectants with an impedance-based system." (PMID 27363011, 2016). "High expression of Hoxd10 correlated with size of tumor, Lauren classification, depth of invasion, lymph node and distant metastasis, and TNM stage." (PMID 26311318, 2015). "MicroRNA-10b (miR-10b) has a prominent role in regulating tumor invasion and metastasis by targeting the HOXD10 transcriptional repressor and has been found up-regulated in several tumor types." (PMID 24897960, 2014). "In tumor tissues HOXD10 was variably expressed with tumors showing a diffuse immunostaining and tumors with a low percentage of stained cancer cells." (PMID 24897960, 2014). "MiR-10b is a potent pro-metastatic metastamiR and previous studies have shown that miR-10b targets several tumor suppressors such as, HOXD10, KLF4, TIAM1 and others." (PMID 25426550, 2014).
tumor (continued). "miR-10b has a prominent role in regulating tumor invasion and metastasis by targeting the HOXD10, a transcriptional repressor involved in cellular migration and extracellular modelling such as RhoC, uPAR, α3-integrin and MT1-MMP." (PMID 24897960, 2014). "Lower HoxD10 gene mRNA levels were found in 46.67% (28/60) of the tumours and showed statistically significant association with grade III tumours (P < 0.001)." (PMID 24634677, 2014). "The variables included in the final multivariate models were: HOXD10 Immunohistochemical positivity, patient age, tumor site and tumor stage." (PMID 25301728, 2014). "The variables included in the final multivariate models were: HOXD10 positivity, patient age, tumor site and tumor stage." (PMID 25301728, 2014). "Its expression is progressively reduced in epithelial cells as malignancy increases in breast tumors and restored Hoxd10 activity inhibits tumor development in mouse xenografts and impairs migration of tumor cells." (PMID 21957483, 2011). "For instance, miR-10b overexpression leads to tumor invasion and metastasis by suppressing HOXD10 and indirectly activating the prometastatic gene RHOC." (PMID 19664288, 2009). "However, HOXD10 overexpression reversed the alterations induced by miR-23a overexpression, therefore indicating HOXD10’s role as a tumor suppressor in GBM and a regulatory axis between miR-23a and HOXD10." (PMID 39858044, 2025). "There has been growing evidence to suggest that HOXD10 functions as a tumor suppressor." (PMID 39858044, 2025). "HOXD10 is a key transcription factor with known tumor-suppressive effects in various cancers." (PMID 40148674, 2025). "Modules 9 and 10 include HOXB13 and HOXD10, both of which belong to the HOX gene family and are associated with cell migration and invasive capacity, and both transcription factors showed upregulation in Il1r2−/− tumor cells." (PMID 40767963, 2025). "HOXD10 is a tumor suppressor involved in the malignancies of many different tissue types." (PMID 38886487, 2024). "Our results signify that upregulation of Twist under Id2 knockdown may lead to HOXD10 reduction and probably block or reduce its tumor suppressor activities." (PMID 35982951, 2022). "In conclusion, we demonstrated that HOXD10 acts as a tumor suppressor in CCRCC." (PMID 34825321, 2022). "Consistent with this, our study observed that HOXD10 suppressed cell migration and invasion and that the low level of HOXD10 was associated with metastasis in CRC, highlighting the critical role of IGFBP3 in HOXD10-mediated tumor-suppressive effect." (PMID 34790580, 2021). "HOXD10 has also been verified as the primary effector that negatively regulates metastasis in cancers, and it was demonstrated to have an inhibitory influence on tumor cell proliferation." (PMID 34022794, 2021). "HOXD10 induces reversion of tumor phenotype in 3D culture conditions in breast cancer." (PMID 33958005, 2021). "Thirdly, we showed the biological relevance of HOXD10 as a tumor-suppressive DNA in CRC." (PMID 34790580, 2021). "Mechanistically, we found that miR-501 promotes tumor progression by directly targeting HOXD10." (PMID 34022794, 2021). "Together, these results suggest that HOXD10 exerts tumor-suppressive functions in CRC." (PMID 34790580, 2021). "HOXD10 is regarded as the primary effector that negatively regulates neoplasm metastasis." (PMID 30683109, 2019). "In conclusion, the high methylation and low relative mRNA expression of HOXD10 in CRC tissue microarray data, cell lines, and tumor tissue samples, combined with the loss of function associated with the AKT/MAPK signaling pathway for the role as anti-oncogenes in the pathogenesis of CRC." (PMID 30683109, 2019). "Another study using 7 cell lines and 68 primary tumours has proposed a similar function for HOXD10, and revealed that HOXD10 was inhibited by miRNA-10b, resulting in increased migration and cell invasion via matrix metallopeptidase 14 and ras homolog family member C." (PMID 31382546, 2019).
tumor (continued). "The tumor weight was significantly reduced after re-expression of HOXD10 (P < 0.05)." (PMID 29075359, 2017). "Recent studies suggest that HoxD10 functions as a candidate tumor suppressor." (PMID 27285765, 2016). "Moreover, miR-10b was shown to be able to promote the invasion and metastasis of tumor cells through post-transcriptional regulation of HOXD10." (PMID 26392359, 2015). "This study identifies miR-10b as an exosomal microRNA that promotes cell invasion in HMLE cells by targeting HOXD10, suggesting that invasive tumor cells may use exosomal microRNAs as a means for their advance." (PMID 25428807, 2014). "However, little is known about the mechanisms of how HoxD10 exerts its functions in carcinogenesis and tumor progression." (PMID 24386080, 2013). "Accumulating evidence suggests that HOXD10 also acts as a tumor suppressor in human malignancies." (PMID 24305689, 2013). "However, PTCSUV-high in our study exhibited high expression levels of HOXD10, which might be related to large tumor size." (PMID 38745021, 2024). "Thus, HOXD10 may be involved in cancer development through the alteration of the tumor microenvironment by granzyme A." (PMID 38356716, 2024). "Although pre-ranked GSEA analysis for RP11-366F6.2 returned no significantly gene sets, examining the functional roles of deregulated genes (such as MAGEA4, MAGEA10, HOXD10 and IGF2BP1) in the leading edge set indicated RP11-366F6.2 might be associated with tumor invasion and metastasis." (PMID 32174965, 2020). "Mechanistically, miR-10b-5p promotes metastasis by targeting tumor suppressor genes such as KLF4 and HOXD10, leading to the upregulation of invasion-related factors like MMP14." (PMID 39796267, 2025). "In CRC, miR-10b-5p is upregulated, enhancing cell migration and invasion by targeting the tumor suppressor HOXD10 and increasing RHOC expression, thereby supporting tumor aggressiveness." (PMID 39796267, 2025). "In our data showed that HOXD10 is lowly expressed in EOC cells compared with IOSE, which is consistent with previous studies in tumor." (PMID 38356716, 2024). "Of note, the HOXD10 and HOXA3 homeobox genes showed a hypermethylated DMR with a greater than 0.2 change in the beta value in every tumor tissue type in the present study." (PMID 38886487, 2024). "A total of five selected tumor antigens, including IGF2BP3, DPCR1, HOXD10, TRIM7, and ZIC5 were identified as promising candidates for mRNA vaccine." (PMID 35593226, 2022). "Taken together, these results suggested the prognosis‐related tumor antigens including IGF2BP3, DPCR1, HOXD10, TRIM7, and ZIC5 were promising targets of being developed as mRNA vaccines against COAD." (PMID 35593226, 2022). "A total of five tumor antigens with prognostic values were identified, including IGF2BP3, DPCR1, HOXD10, TRIM7, and ZIC5." (PMID 35593226, 2022). "To investigate the role of HOXD10 methylation in CRC, we first evaluated HOXD10 methylation in tumor and normal tissues from TCGA database and our cohort." (PMID 34790580, 2021). "Both AMOT-p80 and miR-146a, identified as HOXD10 targets in HNSCC, can represent therapeutic targets for specific tumor stages." (PMID 33763449, 2020). "Previous studies have revealed that microRNA-10b promotes the metastasis of a variety of tumor cells by regulating Bim, TFAP2C, P16, P21, E-cadherin, CD138, RHOC, RhoC, uPAR, MMP-2, MMP-9, HOXD10, etc 23-29." (PMID 31592231, 2019). "Especially after injection of constitutive A673 sh.HOXD10 and sh.HOXD11 transfectants, the amount of tumor cells in the bone marrow was clearly reduced." (PMID 27363011, 2016). "In contrast to DKK2, stable knock down of HOXD genes did not significantly influence bone invasiveness, although suppression of HOXD10, HOXD11 and HOXD13 seemed to slightly reduce the invasive growth potential of tumor cells in the bone marrow." (PMID 27363011, 2016).
tumor (continued). "Several of these genes were differentially expressed between tumour and normal tissue, and two, HOXB9 and HOXD10, were highly expressed in pre-malignant and primary tumour tissue but not in metastases or normal cells." (PMID 25525461, 2014). "HOXA5, HOXD10 and HOXD11 showed the highest expression levels and their up-regulation was then validated by qRT-PCR in tumor samples as well as in cell lines." (PMID 22227861, 2012). "We therefore combined the expression values for the genes identified above (DDIT3, HOXD10, PDE1C, PLS3, PTEN and TUSC3) into a single value per tumor sample, termed 'GNS signature score'." (PMID 23046790, 2012). "The differential roles of HOXD10 in various stages of GBM suggest that its high expression may modulate the activity of this pathway, exerting multifaceted effects on tumor progression." (PMID 40302809, 2025). "While the role of HOXD10 in PTC is currently unknown, evidence supports that HOXD10 has a crucial role as a prognostic indicator while also functioning as a potential tumor suppressor gene in PTC, however further studies are warranted." (PMID 39858044, 2025). "However, their transfection experiments indicated that miR-10b enhances metastatic potential by targeting tumor-suppressor genes KLF4 and HOXD10." (PMID 40486882, 2025). "We also identified three DEGs (HOXD10, IFNA1, and FER1L6) related to tumor size." (PMID 38745021, 2024). "Moreover, the gastrodin treatment led to decreased levels of KI67 and PCNA protein expression and increased levels of HOXD10 and ACSL4 in the tumor tissues compared to the DMSO treatment." (PMID 38138552, 2023). "Moreover, HOXC8, HOXD10, and HOXD11 were confirmed to be involved in biological processes related to tumor formation and progression, such as clone formation and cell metastasis." (PMID 36718148, 2023). "Analysis of tumor immune infiltration showed the elevated expression levels of IGF2BP3, DPCR1, HOXD10, TRIM7, and ZIC5 tended to be correlated with the increased tumor infiltrating B cells, CD8+ T cells, CD4+ T cells, and APCs including macrophages and DCs in COAD patients." (PMID 35593226, 2022). "HOXB9, HOXD10 and HOXA5 were expressed at low levels in GC and acted as tumour suppressors." (PMID 32907552, 2020). "In miR-23a-overexpressing GBM cells, HOXD10 protein levels were dramatically decreased, and mRNA levels of invasion- and GMT-related molecules were markedly altered with polarized formation of focal adhesions, resulting in profound tumor invasion." (PMID 30603114, 2018). "Analyzing by Cox proportional hazards model, HOXD10 methylation was not an independent prognostic marker for 3-year OS after adjusting for tumor differentiation, vessel cancerous embolus, and TNM stage." (PMID 29075359, 2017). "While, according to Cox proportional hazards model analysis, HOXD10 methylation was not an independent prognostic factor for 3-year OS after adjusting for tumor differentiation, vessel cancerous embolus, and TNM stage (P = 0.127)." (PMID 29075359, 2017). "HOXD10 shRNA infectants formed lung tumors indistinguishable from control infectants with increased appearance of tumor nodules within the liver (right)." (PMID 27363011, 2016). "Thus HOXD10 and D11, consistently highly expressed in HNSCC cell lines, macro-dissected tumor tissue samples, and in publicly available tissue microarray data from patients with HNSCC, were selected as candidate genes for further study." (PMID 25301728, 2014). "This association remained significant after adjustment for other clinicopathological variables such as age, tumor stage, smoking and tobacco habit indicating HOXD10 expression is independent of such factors." (PMID 25301728, 2014). "In conclusion, the strikingly high relative expression of HOXD10 and D11 in HNSCC cell lines, tumor tissue samples, and HOXD10 in the tissue microarray data, combined with the loss of function associated with their targeted knockdown argue for their role as oncogenes in the pathogenesis of HNSCC." (PMID 25301728, 2014).
tumor (continued). "Moreover, the protein level of HOXD10 was notably decreased in SHG44, U87, and U251 cells compared to non-tumor brain tissue as normal control." (PMID 24305689, 2013). "We also showed that miRNA-23a could induce U251 and U87 cell invasion, at least partially, via targeting HOXD10 and further modulating the expression of MMP-14, a crucial tumor invasion factor." (PMID 24305689, 2013). "For each patient, HOXD10 and HOXD11 but not HOXB2 mRNA expression was gradually elevated in LM, PCA and N tissues, indicating the oncogenic potential of tumor aggressiveness in PSCC." (PMID 36151071, 2022). "When analyzing the frequency of detectable gene expression per tumor sample (presence/absence), no detectable expression of HOXA5 was observed in one case, while absence of amplification of either HOXD10 or HOXD11 transcripts was observed in two cases." (PMID 22227861, 2012). "Interestingly, HOXD10, HOXD11 and HOXD13 knock down significantly decreased the number of TRAP+ cells within tumor tissue while their number in bones was not affected." (PMID 27363011, 2016).